RNU6-199P (RNA, U6 small nuclear 199, pseudogene)
Gene: Small nuclear RNA gene on chromosome 12 (51,162,901 to 51,163,007, forward strand). Ensembl gene ENSG00000199824.
Homologues: Orthologues: chimpanzee U6 (99% identical), macaque U6 (97% identical), rabbit U6 (91% identical), dog U6 (84% identical), guinea pig U6 (82% identical), mouse Gm23848 (80% identical). Paralogues in human: RNU6-1060P (92% identical), RNU6-116P (91% identical), RNU6-140P (91% identical), RNU6-15P (91% identical), RNU6-41P (91% identical), RNU6-536P (91% identical), RNU6-1019P (90% identical), RNU6-1122P (90% identical), RNU6-1152P (90% identical), RNU6-17P (90% identical), RNU6-18P (90% identical), RNU6-19P (90% identical), and 1285 more.